LEP (leptin)
Diseases named in the same sentence as LEP in open-access papers (continued):
Sharing a sentence is not in itself a finding about the gene and the disease.
atherosclerosis (232 papers, 2007 to 2026). A disease characterized by the build-up of fatty material and calcium deposition in the arterial wall resulting in partial or complete occlusion of the arterial lumen. "Given that atherosclerosis is a major cause of CVDs, researchers have examined the effects of leptin on atherosclerosis in the classic atherosclerotic-prone mouse model." (PMID 40868889, 2025). "Leptin’s involvement in the inflammatory processes underlying atherosclerosis has generated interest in its potential as a biomarker for cardiovascular disease." (PMID 40362168, 2025). "Leptin’s role in promoting inflammation further exacerbates atherosclerosis and the risk of thrombotic events." (PMID 40362168, 2025). "Surprisingly in female SLE patients, elevated leptin levels are independently correlated with a higher risk of atherosclerosis." (PMID 41476956, 2025). "Excess abdominal adiposity is linked to the production of proinflammatory cytokines and the development of leptin resistance, which contributes to chronic body inflammation and is implicated in the pathophysiology of atherosclerosis and cardiovascular disease." (PMID 38921434, 2024). "In animal studies, leptin administration increased atherosclerosis and thrombosis, while leptin deficiency reduced atherogenesis." (PMID 39335491, 2024). "In this study, elevated leptin levels have been linked to the development of atherosclerosis and have been identified as an independent predictor of carotid intima-media thickness (cIMT)." (PMID 39335642, 2024). "A study including 192 RA patients suggests that leptin is associated with the degree of atherosclerosis and plaque formation, independently of other cardiovascular risk factors." (PMID 38764705, 2024). "The adipokines leptin and adiponectin have been associated with atherosclerosis and the risk of cerebral infarcts." (PMID 38686200, 2024). "Leptin has previously been implicated in the development of atherosclerosis due to the presence of the leptin receptor in atherosclerotic lesions." (PMID 36853380, 2023). "Many studies have shown that abnormal leptin levels, such as hyperleptinemia, are closely associated with common risk factors for atherosclerosis (AS)." (PMID 37986371, 2023). "Leptin and adiponectin are the most common adipose tissue-derived cytokines that have shown an association with the occurrence of atherosclerosis and stroke, respectively." (PMID 37342754, 2023). "In chronic obesity, it is commonly accepted that leptin becomes elevated, while adiponectin becomes decreased and results in a decreased adiponectin/leptin ratio, which predisposes to accelerated atherosclerosis and increased risk of CCVD." (PMID 36984562, 2023). "The association between serum leptin levels and atherosclerosis or cardiovascular disease was investigated in another study unrelated to RA." (PMID 35346353, 2022). "Leptin is regarded as an independent risk factor for atherosclerosis that exerts a variety of atherogenic effects." (PMID 36345357, 2022). "All components were associated with at least one single- or multi-site atherosclerosis measure, with the exception of leptin and TIMP-1 (P < 0.05)." (PMID 35039093, 2022). "Leptin has been shown to modulate the expression of several vascular genes associated with atherosclerosis and abnormal angiogenesis including cytokines, chemokines, growth factors and extracellular matrix proteins." (PMID 34064112, 2021). "Increased leptin levels predispose the development of atherosclerosis, by inducing the production of IL-6, IL-12, and TNFα, which plays a significant role in atherogenesis." (PMID 34836100, 2021). "In general, an increase in leptin in the AT localized in the epicardium and CAs is considered as an unfavorable factor associated with the progression of atherosclerosis." (PMID 33735200, 2021).
atherosclerosis (continued). "Adipokines, including adiponectin, leptin, resistin, omentin, visfatin, chemoattractant and retinol binding protein 4, are considered to be risk factors for atherosclerosis." (PMID 34122426, 2021). "Because adiponectin is more closely associated with atherosclerosis as a protective adipocytokine than leptin, our data suggest that IMAT expansion reflects a cardiovascular aggressive fat distribution type." (PMID 34780545, 2021). "Previous studies have shown a harmful effect of leptin in the pathogenesis of atherosclerosis and demonstrated that leptin was an independent risk factor for CAD." (PMID 33148166, 2020). "Leptin-deficient mice exhibit atherosclerotic lesions and leptin administration reduces atherosclerosis through the reduction of hypercholesterolemia and liver steatosis as well as through the upregulation of the atheroprotective adiponectin." (PMID 31500090, 2019). "In summary, the present study has revealed that bLF can decrease serum Hcy, leptin and several traditional risk factors, which are connected with atherosclerosis development such as TC, TG, LDL-C and ApoB in rats fed with high-cholesterol diet." (PMID 30680078, 2018). "Adipocytokines such as leptin and resistin were associated with inflammation but they did not seem to be directly related to parameters of endothelial dysfunction and atherosclerosis in HD patients." (PMID 28747175, 2017). "Leptin is believed to cause atherosclerosis by promoting the proliferation and migration of vascular smooth muscle and endothelial cells, thus inducing neointimal growth." (PMID 26064110, 2015). "Over the years, leptin has been implicated in the development of atherosclerosis due to the presence of leptin receptor in the different compartments of atherosclerotic lesions." (PMID 26064110, 2015). "First, we examined the association between FMD and plasma leptin levels or clinical risk factors for atherosclerosis by simple linear regression analyses for the total population and then for lean and overweight subjects separately." (PMID 24410779, 2014). "Because these two adipokines, namely, leptin and adiponectin, are closely linked to fat metabolism and are considered as an important mediators linking adiposity to atherosclerosis, we calculated the leptin to adiponectin ratio in both groups." (PMID 24550983, 2014). "Thereby, studies performed on humans and animals have shown that adiponectin, apelin, or omentin exerts antiatherogenic effects through various mechanisms, while leptin, resistin, and visfatin are associated with atherosclerosis." (PMID 24616817, 2014). "An uncommon polymorphism in the leptin gene has been associated with carotid intima-medial thickness, a marker of atherosclerosis, in man." (PMID 23122912, 2013). "Experimental studies suggest a role for leptin as a causative or contributing factor in the pathogenesis of atherosclerosis." (PMID 20066136, 2008). "Multiple non-Framingham inflammatory biomarkers, such as plasma soluble TNF-like weak inducer of apoptosis (sTWEAK), dysfunctional pro-inflammatory high-density lipoprotein (HDL) (piHDL), leptin, and homocysteine, are independently linked to atherosclerosis in SLE." (PMID 36293458, 2022). "Among them, leptin, resistin, visfatin, chemoattractant and retinol binding protein 4 may be the common pathogenic factors of psoriasis and atherosclerosis." (PMID 34122426, 2021). "Whether the associations seen between leptin and different SNPs, atherosclerosis, and CAD could be applied to patients throughout the world requires more investigation." (PMID 34178553, 2021). "The extent of atherosclerosis and severity is associated with leptin levels." (PMID 32949971, 2020). "Inflammation is a hallmark of atherosclerosis, and the humoral markers (leptin and adiponectin) mediate the proinflammatory and anti-inflammatory responses, respectively, which may lead to ischemic stroke." (PMID 31412946, 2019).
atherosclerosis (continued). "Leptin has been reported to stimulate p38 mitogen-activated protein kinase (p38MAPK) pathway in different cell types and the p38MAPK pathway also participated in the regulation of physiological processes associated with atherosclerosis." (PMID 27663646, 2016). "Thus, in addition to its pleiotropic hormonal functions regulating metabolic, immune, and endocrine functions, leptin has been implicated in the process of atherosclerosis via multiple avenues." (PMID 23316287, 2012). "In fact, very obese, leptin-deficient mice have been found to be protected from atherosclerosis despite all of the metabolic risk factors, suggesting that this hormone may directly contribute to the risk of vascular disease." (PMID 20847813, 2010). "Additionally, the exercise significantly reduces arterial stiffness in obese adolescent girls, suggesting that the reduction in leptin levels is associated with improved arterial function, which may contribute to a reduced risk of atherosclerosis." (PMID 40861271, 2025). "Role of leptin on atherosclerosis might be overriden by other uremia-related CV risk factors." (PMID 28747175, 2017). "Moreover, hyperleptinemia has been associated with subclinical markers of atherosclerosis such as coronary calcifications and carotid artery intima-media thickness, indeed leptin inhibition has been postulated to be a promising strategy to slow atherogenesis in hyperleptinemic individuals." (PMID 29190710, 2017). "Although the leptin and melanocortin systems are tightly linked, we asked the question of whether obesity induced by defects in the melanocortin system has similar effects on the development of atherosclerosis." (PMID 28030540, 2016). "High leptin levels may help to identify patients with SLE at risk of atherosclerosis." (PMID 23304154, 2012). "Therefore, when chronically elevated concentrations of leptin are seen in obese individuals, this may indicate a predisposition to progression of atherosclerosis in these individuals." (PMID 20847813, 2010). "Various studies have shown that leptin-treated mice have elevated levels of various markers of oxidative stress, including malonyldialdehdye, peroxides, isoprostanes and oxidized lipoproteins, a hallmark feature of atherosclerosis, as well as reduction in anti-oxidant molecules, such as glutathione." (PMID 20066136, 2008). "Nevertheless, leptin can become one of the key factors in the synergy of atherosclerosis and frailty, considerably increasing mortality." (PMID 41594231, 2026). "The adipose tissue releases adipokines that have a pro-inflammatory (leptin, IL-6) or anti-inflammatory (adiponectin) role in atherosclerosis." (PMID 40137085, 2025). "Hyperleptinemia in SLE patients promotes Th17 responses and correlates with atherosclerosis; leptin blockade improves lupus nephritis in mice." (PMID 41476956, 2025). "Consistent with findings from animal studies, research in humans has also demonstrated that exercise can reduce leptin expression, thereby alleviating atherosclerosis." (PMID 40861271, 2025). "Overall, investigations have revealed that engaging in exercise can diminish leptin levels in those with atherosclerosis, thereby reducing the pathological development of atherosclerosis." (PMID 40861271, 2025). "In a comprehensive review, leptin is portrayed as a potential modulator of atherosclerosis, the impact of which is contingent upon its concentration in the blood." (PMID 40861271, 2025). "Evidence suggests that adipokines such as adiponectin, leptin, and interleukin-6 can play important roles in atherosclerosis development, progression, as well as regression." (PMID 39684379, 2024). "Leptin also induces the proliferation, migration, and calcification of vascular smooth muscle cells (VSMCs), contributing to the progression of atherosclerosis." (PMID 39335642, 2024).
atherosclerosis (continued). "Future investigations might focus specifically on the effects of leptin supplementation as well as transplantation of leptin-deficient adipose tissues from ob/ob mice to confirm the contribution of leptin signaling in lipodystrophy-associated atherosclerosis in Seipin/Apoe dKO mice." (PMID 38525541, 2024). "The use of leptin to lower weight and reduce risks of atherosclerosis can be performed to improve the health outcomes of DM patients." (PMID 38892018, 2024). "Leptin contributes to atherosclerosis by triggering inflammatory responses and oxidative stress and enhancing platelet aggregation and migration." (PMID 38091015, 2024). "Metabolically, the cytokines secreted by visceral fat, including leptin, adiponectin, and TNF-α, can incite inflammatory responses and cause endothelial dysfunction, thereby facilitating atherosclerosis and heightening the risk of CVD." (PMID 39458542, 2024). "Apart from these links to atherosclerosis, leptin, a hormone produced by adipose tissue and osteoblasts, plays a crucial role in mineral and bone metabolism." (PMID 39062887, 2024). "First, adipokines such as lipocalin, leptin and chemotaxin promote the formation of atherosclerosis but they also participate in the remodeling of bones." (PMID 38836228, 2024). "In this study, we investigated the relationship between an early measure of subclinical atherosclerosis, cIMT, and adipokine levels, specifically adiponectin, leptin, and resistin, in a Hispanic/Latino cohort." (PMID 37653519, 2023). "CHI3L1, CD36, IL-18, and RARRES2 genes have also been reported to be associated with IR, whereas APOA1, CD36, LEP, FN1, and CETP genes were found to be associated with atherosclerosis." (PMID 36984867, 2023). "In this cross-sectional study of Mexican Americans in the CCHC cohort, we investigated the association of adiponectin, leptin, resistin, and composite measures of ARI and LAR with an early marker of atherosclerosis, cIMT, both across and within sexes." (PMID 37653519, 2023). "Lastly, Leptin is both a drug capable of reducing free radicals, OS, and atherosclerosis in patients with OSAS." (PMID 36982552, 2023). "Other effects of leptin include activation of inflammatory responses, oxidative stress, thrombosis, and atherosclerosis, thereby resulting in endothelial dysfunction and atherosclerotic plaque." (PMID 36901837, 2023). "Adipokines in general and leptin in particular, in addition to hindering insulin functions, can promote atherosclerosis through direct immunomodulation in vascular tissue and, in turn, further promote the expression of proinflammatory cytokines." (PMID 36145322, 2022). "The downregulation of acid sphingomyelinase improves endothelial leptin resistance and atherosclerosis." (PMID 35111371, 2022). "Adipokines, such as leptin, adiponectin and C1q tumor necrosis factor-related protein 9, have been reported to be involved in the occurrence and development of atherosclerosis." (PMID 35902881, 2022). "Leptin resistance in endothelial cells leads to vascular endothelial dysfunction, which marks the onset of atherosclerosis." (PMID 35111371, 2022). "CD36 is also a worthwhile target for further investigation in the treatment of cardiovascular disease, as CD36 low molecular weight inhibitors reduced both atherosclerosis and metabolic abnormalities in a leptin and LDL receptor double knockout mouse model." (PMID 36551839, 2022). "Leptin facilitates the differentiation of monocytes into macrophages and accelerates the development of cardiovascular complications such as atherosclerosis." (PMID 36499312, 2022). "Elevated leptin in psoriasis patients has been shown to correlate with severity of skin disease and indices of subclinical atherosclerosis." (PMID 36145322, 2022). "Elevated leptin correlates with atherosclerosis and is an independent predictor of carotid intima-media thickness (cIMT) progression." (PMID 36499312, 2022).
atherosclerosis (continued). "Leptin and visfatin have been proposed as clinical markers of atherosclerosis, endothelial dysfunction, and vascular injury in cardiovascular disease." (PMID 34422210, 2021). "Such disparate findings in the current literature have largely confounded our understanding of the role of leptin in atherosclerosis." (PMID 34064112, 2021). "Chronically elevated leptin concentrations increase oxidative stress, promote thrombus formation as well as facilitate vascular inflammation and atherosclerosis." (PMID 34064112, 2021). "From a molecular perspective, leptin plays a role in atherosclerosis initiation by the hyper-production of reactive oxygen species (ROS) in endothelial cells." (PMID 34603210, 2021). "Among these adipokines, adiponectin and omentin have a protective role in the process of atherosclerosis, while leptin was shown to promote atherosclerosis development." (PMID 34528389, 2021). "This higher leptin level was correlated to higher macrophage infiltration due to its effect as a macrophage recruiter, which further increases the rate of atherosclerosis progression." (PMID 33562069, 2021). "Many researchers have reported that, among SLE patients compared to healthy people, serum leptin levels are higher, which is associated with SLE disease activity, atherosclerosis, etc." (PMID 35027962, 2021). "Various studies have been performed on the effects of biologics on lipids, leptin, adiponectin, and imaging markers of atherosclerosis." (PMID 34680168, 2021). "Currently the data on the role of leptin as a promoter of atherosclerosis in CKD are limited and at times conflicting." (PMID 32024124, 2020). "Fourth, leptin has been shown to upregulate inflammatory immune responses by increasing cytokines and growth factors, further inducing atherosclerosis and endothelial dysfunction." (PMID 32403968, 2020). "Despite multiple studies suggesting that alteration of leptin signalling enhances atherosclerosis progression, the precise mechanism by which this occurs has not been clarified yet." (PMID 32816039, 2020). "Investigators believe that a high level of leptin is related to low arterial extensibility and participates in the pathogenesis of atherosclerosis via mechanisms different from vascular relaxation." (PMID 32121175, 2020). "As regards its effects on atherosclerosis, leptin was shown to play a critical role in the early phase of this disease." (PMID 33192583, 2020). "The expression level of leptin, a cytokine that has a known role in the pathogenesis of atherosclerosis, was significantly lower in Gal12−/− mice than in Gal12+/+." (PMID 32752134, 2020). "Obese patients typically show a high circulating level of leptin and leptin resistance Leptin pro-angiogenic properties have been described directly related to endothelial dysfunction and atherosclerosis development." (PMID 33643281, 2020). "Leptin can have a direct effect on endothelial and vascular smooth muscle cells and high level of leptin is involved in the pathogenesis of atherosclerosis." (PMID 33148166, 2020). "VEGF is known to be induced by ROS and to promote atherosclerosis and leptin is an adipokine and has been shown to stimulate the immune responses and to increase sympathetic drive." (PMID 32949971, 2020). "It has been suggested that leptin is one of the mediators of atherosclerosis by favoring an inflammatory state that promotes the recruiting of monocytes to the arterial intima, and inducing proinflammatory cytokines." (PMID 32824322, 2020). "Adipokines retinol-binding protein 4 (RBP4), resistin, and leptin are reported to support the progression of atherosclerosis, while adiponectin has protective actions against plaque formation." (PMID 32947976, 2020). "Recently, by increasing sympathetic tone and thus elevating blood pressure, leptin was found to be related to atherosclerosis in patients with cardiovascular disease." (PMID 29304064, 2018).